STON1 (stonin 1)
Description:
May be involved in the endocytic machinery.
Synonyms: SALF; SBLF; stoned-b1; STNB1
Tractability: PROTAC: ubiquitination databases record sites on it.
Gene: Protein-coding gene on chromosome 2 (48,529,376 to 48,598,922, forward strand). Ensembl gene ENSG00000243244.
Subcellular location: Cytoplasm; Membrane
Pathways (Reactome):
Vesicle-mediated transport: Cargo recognition for clathrin-mediated endocytosis; Clathrin-mediated endocytosis
Gene Ontology:
Molecular function: clathrin adaptor activity; cargo adaptor activity
Biological process: regulation of endocytosis; clathrin-dependent endocytosis; synaptic vesicle endocytosis; endocytosis
Cellular component: AP-2 adaptor complex; cytosol; synaptic vesicle; cell leading edge; clathrin-coated pit; cytoplasm; membrane
Genetic constraint (gnomAD): Loss-of-function variants: 76 observed, 60.38 expected, observed/expected ratio (o/e) 1.26, 90% interval 1.04 to 1.52. The upper end of that interval is the gene's LOEUF score, 1.52, which puts it in group 6 of 6, group 1 being the genes least tolerant of losing a copy. Missense variants: 1,164 observed, 850.64 expected, observed/expected ratio (o/e) 1.37, 90% interval 1.3 to 1.44. Synonymous variants: 363 observed, 310.19 expected, observed/expected ratio (o/e) 1.17, 90% interval 1.07 to 1.28.
Homologues: Orthologues: chimpanzee STON1 (97% identical), macaque STON1 (93% identical), dog STON1 (87% identical), pig STON1 (86% identical), rabbit STON1 (83% identical), guinea pig STON1 (83% identical), mouse Ston1 (76% identical), rat Ston1 (75% identical), tropical clawed frog ston1 (54% identical), zebrafish STON1 (34% identical). Paralogues in human: STON2 (36% identical), AP1M1 (13% identical), AP4M1 (12% identical), AP1M2 (12% identical), AP2M1 (11% identical), AP3M1 (10% identical), AP3M2 (9% identical).
Diseases named in the same sentence as STON1 in open-access papers:
STON1 is named in the same sentence as 28 diseases in open-access papers, as found by Europe PMC text mining. Sharing a sentence is not in itself a finding about the gene and the disease. The quoted sentences say what the papers report.
polycystic ovaries (2 papers, 2023 to 2024). "In our current study, STON1, a protein-coding gene involved in vesicle transport, was identified as a target gene at the rs13405728 locus in polycystic ovary syndrome." (PMID 36759775, 2023). "The authors showed that in patients with polycystic ovaries, high expression of STON1 may be responsible for the hyperandrogenic phenotype associated with severe metabolic disorders." (PMID 38672173, 2024).
autism (1 paper, 2022). Persistent deficits in social interaction and communication and interaction as well as a markedly restricted repertoire of activity and interest as well as repetitive patterns of behavior. "Our first GWAS reveals that the variants of the STON1 gene may be associated with the variation in sleep quality indicated by the CSHQ score amongst individuals on the autism spectrum." (PMID 35873241, 2022).
bladder urothelial carcinoma (1 paper, 2022). "High expressions of STON1 and C14orf132 were correlated with worse prognosis in bladder urothelial carcinoma and CRC, respectively." (PMID 35681225, 2022).
hyperandrogenism (1 paper, 2021). Excessive secretion of androgens from the adrenal glands or gonads. "In PCOS, high BMI is a common characteristic and was a predictor of hyperandrogenism, consisting of the findings that STON1 was highly expressed in PCOS and PCOS-like models." (PMID 34248847, 2021).
tumor (3 papers, 2022 to 2024). "Moreover, STON1 was positively associated with mismatch repair proteins and negatively correlated with tumor mutational burden." (PMID 36759775, 2023). "Mechanically, low STON1 expression is associated with an aberrant tumor immune microenvironment." (PMID 36759775, 2023). "Cancer-Immunity Cycle is a multistep fine-regulated network, so we explored the function of STON1 in anti-tumor immune activities to compare the difference between the low and high STON1 groups." (PMID 36759775, 2023). "Collectively, lower STON1 expression in KIRC indicates tumor progression and worse survival outcome." (PMID 36759775, 2023). "Additionally, the relationship between STON1 expression and the tumor microenvironment was primarily presented with Kaplan–Meier survival analysis." (PMID 36759775, 2023). "Our current study provides new insights into the function of STON1 in the tumor microenvironment." (PMID 36759775, 2023). "We undertook bioinformatics analyses of the expression and clinical significance of STON1 in KIRC through a series of public databases, and the role of STON1 in the tumor microenvironment and the predictive value for immunotherapy and targeted treatment in KIRC were identified with R packages." (PMID 36759775, 2023). "Since genes highly expressed in the immune microenvironment are expected to have negative associations with tumor purity, ID4, and STON1 which had an unsignificant association with tumor purity (p > 0.05) were excluded." (PMID 35432538, 2022).
cancer (2 papers, 2023 to 2024). A tumor composed of atypical neoplastic, often pleomorphic cells that invade other tissues. "The heatmap also indicated that STON1 expression was obviously negatively related to most of these cancer-immunity cycle pathway signatures." (PMID 36759775, 2023). "Our current research has revealed the potential new role of STON1 in cancer, special for KIRC." (PMID 36759775, 2023). "However, to date, no reports have published the underlying functions of STON1 in cancer, especially immune functions." (PMID 36759775, 2023). "Stonin1 (STON1) is an endocytic protein but its role in cancer remains unclear." (PMID 36759775, 2023).
STON1 also shares sentences with these, for which no sentence is quoted: basal cell skin cancer (1 paper); bladder carcinoma (1); breast invasive carcinoma (1); clear cell kidney carcinoma (1); colon adenocarcinoma (1); colon carcinoma (1); colorectal cancer (1); endometriosis (1); glioma (1); head and neck squamous cell carcinoma (1); kidney chromophobe (1); lung adenocarcinoma (1); lung carcinoma (1); lung squamous cell carcinoma (1); lymph node metastasis (1); metabolic disorders (1); pancreatic duct adenocarcinoma (1); papillary renal cell carcinoma (1); prostate adenocarcinoma (1); seizure disorder (1); thyroid carcinoma (1); uterine corpus endometrial carcinoma (1).